DNAJA1 (DnaJ heat shock protein family (Hsp40) member A1)
Description:
Co-chaperone for HSPA8/Hsc70. Stimulates ATP hydrolysis, but not the folding of unfolded proteins mediated by HSPA1A (in vitro). Plays a role in protein transport into mitochondria via its role as co-chaperone. Functions as a co-chaperone for HSPA1B and negatively regulates the translocation of BAX from the cytosol to mitochondria in response to cellular stress, thereby protecting cells against apoptosis. Promotes apoptosis in response to cellular stress mediated by exposure to anisomycin or UV.
Synonyms: HSJ-2; hDj-2; HDJ2; HSJ2; HSPF4; dj-2; NEDD7; DjA1; HSDJ
Tractability: Small molecule: it belongs to a druggable protein family. PROTAC: ubiquitination databases record sites on it; its protein half-life has been measured; a small molecule that binds it is known.
Gene: Protein-coding gene on chromosome 9 (33,025,206 to 33,039,916, forward strand). Ensembl gene ENSG00000086061.
Subcellular location: Membrane; Cytoplasm; Microsome; Nucleus; Cytoplasm, perinuclear region; Mitochondrion
Subcellular location (Human Protein Atlas): Cytosol; Microtubules
Pathways (Reactome):
Cellular responses to stimuli: HSP90 chaperone cycle for steroid hormone receptors (SHR) in the presence of ligand; Mitochondrial unfolded protein response (UPRmt)
Gene Ontology:
Molecular function: ATPase activator activity; C3HC4-type RING finger domain binding; G protein-coupled receptor binding; Hsp70 protein binding; low-density lipoprotein particle receptor binding; protein binding; protein-folding chaperone binding; Tat protein binding; ubiquitin protein ligase binding; ATP binding; heat shock protein binding
Biological process: negative regulation of apoptotic process; negative regulation of establishment of protein localization to mitochondrion; negative regulation of JUN kinase activity; negative regulation of nitrosative stress-induced intrinsic apoptotic signaling pathway; negative regulation of protein ubiquitination; positive regulation of apoptotic process; protein localization to mitochondrion; regulation of protein transport; protein folding; response to unfolded protein; response to heat
Cellular component: cytosol; extracellular exosome; membrane; microtubule cytoskeleton; cytoplasmic side of endoplasmic reticulum membrane; cytoplasm; mitochondrion; nucleus; perinuclear region of cytoplasm
Genetic constraint (gnomAD): Loss-of-function variants: 20 observed, 37.64 expected, observed/expected ratio (o/e) 0.53, 90% interval 0.37 to 0.77. The upper end of that interval is the gene's LOEUF score, 0.77, which puts it in group 3 of 6, group 1 being the genes least tolerant of losing a copy. Missense variants: 281 observed, 452.73 expected, observed/expected ratio (o/e) 0.62, 90% interval 0.56 to 0.69. Synonymous variants: 146 observed, 148.31 expected, observed/expected ratio (o/e) 0.98, 90% interval 0.86 to 1.13.
Homologues: Orthologues: chimpanzee DNAJA1 (100% identical), dog DNAJA1 (100% identical), guinea pig DNAJA1 (100% identical), macaque DNAJA1 (100% identical), pig DNAJA1 (100% identical), rabbit DNAJA1 (100% identical), mouse Dnaja1 (99% identical), rat Dnaja1 (99% identical), tropical clawed frog dnaja1 (86% identical), zebrafish dnaja1 (70% identical). Paralogues in human: DNAJA4 (74% identical), DNAJA2 (57% identical), DNAJA3 (29% identical).
Diseases named in the same sentence as DNAJA1 in open-access papers:
DNAJA1 is named in the same sentence as 46 diseases in open-access papers, as found by Europe PMC text mining. Sharing a sentence is not in itself a finding about the gene and the disease. The quoted sentences say what the papers report.
pancreatic cancer (9 papers, 2016 to 2023). "These proteins in conjunction with our previously published metabolomics study support a vital role for DNAJA1 in cellular oncogenesis and pancreatic cancer." (PMID 36291603, 2022). "DnaJA1 was downregulated 5-fold in a genomic analysis of cancer cells and targeted as a biomarker in pancreatic cancer." (PMID 35570564, 2022). "In recent years, emerging in tumor-related fields, DNAJA1 has been identified as biomarker for pancreatic cancer and breast cancer." (PMID 35586205, 2022). "Down-regulation of Dnaja1 in pancreatic cancer cells probably reduced the activity of DnaK even under stress conditions, which promoted the occurrence and progression of cancer due to cell proliferation." (PMID 29255456, 2017). "The human protein DNAJA1 has been proposed as a potential therapeutic target for pancreatic cancer, but its cellular and biological functions remain unclear." (PMID 36291603, 2022). "DNAJA1 could induce the radiotherapy resistance of glioblastomas and anticancer drug resistance and suppressed the stress response capabilities of c-Jun and cell survival in pancreatic cancer." (PMID 35586205, 2022). "It is hypothesized that DnaJA1 activates a DnaK protein by making a complex that inhibits the JNK pathway, hyperphosphorylation of c-Jun and antiapoptotic state observed in pancreatic cancer." (PMID 35570564, 2022). "DNAJA1 has been identified as a potential therapeutic target for treating pancreatic ductal adenocarcinoma (PDAC), which accounts for more than 90% of all pancreatic cancers." (PMID 36291603, 2022).
glioblastoma (5 papers, 2016 to 2022). The most malignant astrocytic tumor (WHO grade IV). "Other members have been implicated in cancer development and metastasis, such as DNAJA1 (in glioblastoma and prostate), DNAJB11 (in ovarian tumors), and DNAJC9 (cervical)." (PMID 33810095, 2021). "The down regulation of DNAJA1 in C6 glioblastoma was shown to increase tumorigenicity with the rescued expression of DNAJA1 reversing this behavior." (PMID 36291603, 2022). "A study suggests the tumor suppressive activity, in which knockdown of DNAJA1/HDJ2 promotes spheroid formation, migration, and invasion of C6 rat glioblastoma cells and reduces survival of rats bearing C6 tumor xenografts." (PMID 34948322, 2021). "In the C6 rat glioblastoma model, DnaJA1 suppresses tumor growth and metastatic formation capacity, which is attributed to diminishing relocation of N-cadherin and the activity of metalloproteinases and prevention of the amoeboid-like transition of tumor cells." (PMID 35570564, 2022). "However, it has been shown that inhibition of DnaJA1 can contribute to radiosensitivity of glioblastoma multiforme cells." (PMID 35570564, 2022). "To analyze whether this also functions in a highly malignant brain tumor, we knocked down the expression of Hsp70 (HSPA1A) and its two most abundant co-chaperones, Hdj1 (DNAJB1) and Hdj2 (DNAJA1) in a C6 rat glioblastoma cell line." (PMID 26959111, 2016).
colorectal cancer (4 papers, 2019 to 2023). A primary or metastatic malignant neoplasm that affects the colon or rectum. "Treatment of colorectal cancer cells with KNK437 inhibits the expression of DnaJA1 and the cell cycle progression through destabilization of CDC45." (PMID 31878360, 2019). "Clinicopathologic analyses have shown the markedly increased expression of DnaJA1 in colorectal cancer (CRC) tissues, particularly those of which had developed metastases in lymph node and distant organs." (PMID 31878360, 2019). "DNAJA1/HDJ2 also promotes tumor growth and metastasis in human colorectal cancer (CRC) cell lines by interacting with and stabilizing cell division cycle 45 (CDC45)." (PMID 34948322, 2021).
Huntington disease (4 papers, 2020 to 2022). Huntington disease (HD) is a rare neurodegenerative disorder of the central nervous system characterized by unwanted choreatic movements, behavioral and psychiatric disturbances and dementia. "DNAJA1 enhances formation of aggregation of polyQ74htt in the Huntington’s disease model, reduces aggregation of neurodegenerative disorder-associated tau, and promotes folding of newly synthesized cystic fibrosis transmembrane conductance regulator at the endoplasmic reticulum." (PMID 36316326, 2022). "In particular, the class A cochaperone DNAJA1 as well as the class B cochaperone DNAJB4 are upregulated in patients with AD, PD, and Huntington's disease (HD) compared with age-matched controls." (PMID 32467226, 2020).
Alzheimer disease (3 papers, 2022 to 2024). A progressive, neurodegenerative disease characterized by loss of function and death of nerve cells in several areas of the brain leading to loss of cognitive function such as memory and language. "DNAJA1, the human homolog of Ydj1, has been proven to promote the formation of Amyloid beta 42 (trigger of Alzheimer’s disease) and tumor metastasis." (PMID 38539794, 2024).
breast carcinoma (3 papers, 2021 to 2024). "High DNAJA1/HDJ2 mRNA expression is associated with poor survival in patients with breast cancer, while DNAJA1/HDJ2 promotes an anti-apoptotic phenotype and invasiveness of pancreatic ductal adenocarcinoma cells." (PMID 34948322, 2021). "The expressions of DNAJA1 and DNAJC9 genes were elevated in breast cancer samples and BCSCs, which is considered unfavorable for survival in breast cancer." (PMID 38255948, 2024).
Parkinson disease (3 papers, 2014 to 2022). A progressive degenerative disorder of the central nervous system characterized by loss of dopamine producing neurons in the substantia nigra and the presence of Lewy bodies in the substantia nigra and locus coeruleus. "Among these two genes, DNAJA1 has been implicated in several neurodegenerative diseases including AD and Parkinson’s disease, however, its most significant functional role appears to be the regulation of tau." (PMID 32192109, 2020). "Thus heat-shock, cigarette smoke, or chemical treatments with elesclomol or the HSP90-inhibitor geldanamycin, as well as in chronically challenged tissues in Parkinson's disease, type II, DNAJB1 and DNAJB4 were found to be systematically more over-expressed than type I, DNAJA1 and DNAJA2." (PMID 25988148, 2014).
rheumatoid arthritis (3 papers, 2013 to 2022). A chronic, systemic autoimmune disorder characterized by inflammation in the synovial membranes and articular surfaces. "DNAJA1/HDJ2 is implicated in a variety of diseases, including rheumatoid arthritis, oculopharyngeal muscular dystrophy, cystic fibrosis, and the neurodegenerative diseases." (PMID 34948322, 2021). "One report has demonstrated a regulatory role of Dnaja1 where it inhibits T cell proliferation and induces IL‐10 production by PBMC in rheumatoid arthritis patients." (PMID 36030499, 2022).
glioma (2 papers, 2017 to 2022). A benign or malignant brain and spinal cord tumor that arises from glial cells (astrocytes, oligodendrocytes, ependymal cells).
liver cancer (2 papers, 2022 to 2024). An epithelial or non-epithelial malignant neoplasm that arises from the liver. "The expression of DNAJA1 was associated with clinicopathologic features in liver cancer and correlated strongly with differentiation (P < 0.001), dissemination (P < 0.001), and serum AFP (P = 0.020)." (PMID 35586205, 2022). "In conclusion, our study demonstrates that upregulation of DNAJA1 in liver cancer associates with poor survival of patients." (PMID 35586205, 2022). "Our study shows that DNAJA1 was upregulated in liver cancer tissues and associated closely with poor prognosis, suggesting a role as an oncogene in proliferation and metastasis of liver cancer cells." (PMID 35586205, 2022). "Enhanced expression of DNAJA1 in liver cancer tissues correlates strongly with unfavorable prognosis, highlighting its oncogenic function in liver cancer cell proliferation and metastasis." (PMID 39453509, 2024). "The Kaplan Meier survival analysis showed that higher expression of DNAJA1 predicted poorer survival for liver cancer patients (P < 0.001)." (PMID 35586205, 2022). "As a target of miR-205-5p, DNAJA1 acts as an oncogene in the progression of liver cancer via binding to EF1A1 to reduce the ubiquitination and degradation of EF1A1." (PMID 35586205, 2022). "Mechanistically, as a direct target of miR-205-5p, DNAJA1 promoted proliferation and metastasis of liver cancer cells by stabilizing eukaryotic elongation factor 1A1 (EF1A1)." (PMID 35586205, 2022). "DNAJA1 was obviously upregulated in 43 cases of fresh liver cancer tissues compared to normal livers (P = 0.003) and was either unaltered or downregulated in three cases of cancer tissues versus normal." (PMID 35586205, 2022). "The expression levels of miR-205-5p were downregulated in 43 cases of paired fresh liver cancer tissues and were negatively correlated to the mRNA levels of DNAJA1." (PMID 35586205, 2022). "In this study, we found that miR-205-5p was downregulated in liver cancer, whereas DNAJA1 was highly expressed in liver cancer and negatively correlated with the expression of miR-205-5p, confirming that DNAJA1 was a target gene of miR-205-5p." (PMID 35586205, 2022). "Higher DNAJA1 expression in liver cancer tissues compared to normal was also validated by western blots." (PMID 35586205, 2022). "Taken together, these results demonstrate that DNAJA1 mediates the ubiquitination of EF1A1 via protein interaction in liver cancer." (PMID 35586205, 2022). "To investigate the role of DNAJA1 in liver cancer progression, we first detected endogenous expression of DNAJA1 in six liver cancer cell lines." (PMID 35586205, 2022). "In this study, we explored the functional role of DNAJA1 and the mechanism of regulation in liver cancer." (PMID 35586205, 2022). "We explored the expression pattern of DNAJA1 and its clinicopathologic value in liver cancer." (PMID 35586205, 2022). "As for tumorigenesis, DNAJA1 promoted the proliferation, invasion, and angiogenesis of liver cancer cells in vitro and vivo, possibly by regulation of cell cycle and apoptosis of HCC cells, although the influences of DNAJA1 on apoptosis of these liver cancer cells vary." (PMID 35586205, 2022). "In summary, the upregulation of DNAJA1 correlated with liver cancer progression and could be an independent prognostic indicator for survival of liver cancer patients." (PMID 35586205, 2022). "The mRNA levels of miR-205-5p and DNAJA1 were negatively correlated in liver cancer." (PMID 35586205, 2022). "Our work firstly demonstrates that DNAJA1 promotes liver cancer progression." (PMID 35586205, 2022). "In conclusion, our study reveals that DNAJA1 acts as an oncogene in liver cancer via miR-205-5p/EF1A1 axis and might be a potential biomarker to predict the prognosis for liver cancer patients." (PMID 35586205, 2022). "Strong staining for DNAJA1 was frequently observed in liver cancer." (PMID 35586205, 2022).
liver cancer (continued). "Next, we assessed the role of DNAJA1 in the invasion and angiogenesis of liver cancer." (PMID 35586205, 2022). "DNAJA1 expression was first examined by IHC in 106 cases of paraffin-embedded liver cancer tissues." (PMID 35586205, 2022). "In vivo assays also verified that miR-205 could indeed regulate DNAJA1-induced proliferation and metastasis of liver cancer cells." (PMID 35586205, 2022). "Next, we clarified the potential mechanisms of actin of DNAJA1 in liver cancer." (PMID 35586205, 2022). "However, the role of DNAJA1 in liver cancer is still not well understood." (PMID 35586205, 2022).
neuroblastoma (2 papers, 2022). Neuroblastoma (NB) is the most common solid, extracranial childhood tumor. "In parallel, another study tested HSP40 effects on the AD‐associated protein tau showing that overexpression of DnaJA1 can favor both tau clearance and stabilization dependent on Hsp70 levels in M17 neuroblastoma cells." (PMID 35373908, 2022). "We also found that in the gastric adenocarcinoma cells AGS and neuroblastoma SH-SY5Y cells DnaK binds DnaJA1, a member of the HSP40 family of molecular co-chaperones." (PMID 36386669, 2022).
acute lymphoblastic leukemia (1 paper, 2017). Leukemia with an acute onset, characterized by the presence of lymphoblasts in the bone marrow and the peripheral blood. "For example, HDJ-2 (DNAJA1), due to its high expression in B-lineage acute lymphoblastic leukemia (ALL) cells, has been specifically used as a diagnostic biomarker to detect minimal residual disease." (PMID 28914774, 2017).
bladder carcinoma (1 paper, 2020). "While previous studies have indicated the association between proteomic changes and histone PTMs in response to Hsp90 inhibitor treatment in bladder carcinoma cells, no such association has been shown for DNAJA1 and Histone PTMs40." (PMID 32796891, 2020).
chronic myelogenous leukemia (1 paper, 2021). "By screening the NCI-approved oncology drugs collection in human chronic myelogenous leukemia HAP1 cell line with or without DNAJA1/HDJ2 knockout, 41 compounds, including cabozantinib, clofarabine, and vinblastine, are identified as drugs that show synergy with DNAJA1/HDJ2 loss." (PMID 34948322, 2021).
leishmaniasis (1 paper, 2024). Infectious disease that is transmitted through the bite of hematophagous female phlebotomine sand flies. "Through PPI network analysis, hub genes such as Lcn2, Ltf, Mpo, Dnaja1, Hspa1a, Hspa1b and Hsph1 were screened out and might play important roles in the process of undernutrition promoting leishmaniasis." (PMID 38185681, 2024).
prostate carcinoma (1 paper, 2020). A carcinoma that arises from epithelial cells of the prostate gland. "Our bioinformatic analysis of DNAJA1 expression and mutation clearly identify DNAJA1 as being highly altered in a range of cancers, particularly in prostate cancer." (PMID 32796891, 2020). "Our previous bioinformatics analysis indicated that a large proportion of prostate cancer cells contain either amplification or mutation of DNAJA1 (approximately 18%)." (PMID 32796891, 2020).
proteinopathies (1 paper, 2022). "This goes in line with our observation that YDJ1 does not influence alpha‐synuclein toxicity in yeast, indicating differential roles of Ydj1/DnaJA1 toward some clients implicated in proteinopathies." (PMID 35373908, 2022).
viral infection (1 paper, 2024). "This suggests the role of DNAJA1 in modulating multiple viral infections through diverse mechanisms." (PMID 39591305, 2024).